SUN2 (Sad1 and UNC84 domain containing 2)
Diseases named in the same sentence as SUN2 in open-access papers (continued):
Sharing a sentence is not in itself a finding about the gene and the disease.
infection (8 papers, 2017 to 2026). The state of being infected such as from the introduction of a foreign agent such as serum, vaccine, antigenic substance or organism. "Like SUN1, SUN2 poorly affected the infection of HIV-1 bearing the capsid mutation G208R, which is in agreement with our previous results suggesting that capsid mutations overcome the HIV-1 restriction imposed by overexpression of SUN222." (PMID 34580332, 2021). "Infection was blocked after DNA synthesis, before or at the point of nuclear entry, and was associated with drastic changes in nuclear morphology resulting from SUN2 overexpression." (PMID 29056936, 2017). "Similarly, the infection of replication-competent HIV-1NL4-3 in PHA-P-activated primary CD4+ T cells disrupted the association between SUN2 and lamin A/C, and the disassociation could be restored when HIV-1 replication was blocked with zidovudine (AZT)." (PMID 29717016, 2018). "From 8 days post infection (d p.i.), weights of WT mice gradually declined, while Sun2-/- mice showed weight gain." (PMID 38177122, 2024). "The collective data suggested that SUN2 specifically promotes the replication of flaviviruses through regulating the cytoskeleton remodeling induced by their infection." (PMID 38177122, 2024). "In a neonatal mouse infection model, SUN2 knockout dramatically alleviates the in vivo ZIKV replication and development of neuropathology." (PMID 38177122, 2024). "One possibility is that the interaction between the N-terminal domain of SUN1 or SUN2 with the pre-integration complex negatively affects infection by changing the localization of the core in the nuclear compartment." (PMID 34580332, 2021). "Consistently, up to 90% (25 out of 28) of the ISGs (except for family with sequence similarity 46, member C (FAM46C), heparanase (HPSE), and SUN2) exerted significant facilitation in THP-1-Mφs within 48 h infection of H37Rv." (PMID 30717477, 2019). "SUN2 knockdown significantly increased the infection of HIV-luc/VSV-G and elevated the production of HIV-1 gag mRNA but kept HIV-1 integration at a similar level to that in the off-target controls." (PMID 29717016, 2018). "Sun2 protein expression after shRNA infection was determined by immunoblotting analysis, showing that it was significantly decreased compared with control." (PMID 29163775, 2017). "The infectivity of HIVac-1 GFP LV was severely reduced in THP-1 control cells as well as in THP-1 SUN1 or SUN2 knockout cell clones, and CS treatment rescued infectivity in all cases to infection levels of the wild-type LV." (PMID 28747499, 2017). "We found that GFP reverse transcription products were present at similar levels in control and SUN2 knockout cells 6 h after infection." (PMID 28747499, 2017). "First, bone marrow-derived dendritic cells from SUN2−/− mice display increased permissivity to infection by an HIV-1 mutant that is hypersensitive to blockade by CypA (referred to as HIVac-1)." (PMID 28747499, 2017). "In HSV-1 infection, decreased SUN2 expression could facilitate the progression of infection and the nuclear egress of HSV-1 capsids, possibly by remodeling chromatin and NE organization." (PMID 41557685, 2026). "We further tested role of SUN2 in the infection of RNA viruses belonging to other families, including three positive-strand RNA viruses (SARS-CoV-2, Semliki Forest virus SFV, and encephalomyocarditis virus EMCV) and a negative-strand RNA virus (vesicular stomatitis virus, VSV)." (PMID 38177122, 2024). "Overexpression of SUN2 poorly affected infection by FIV, BIV, EIAV, and B-MLV viruses." (PMID 34580332, 2021). "SUN2 overexpression significantly inhibited the infection of HIV-luc/NL4-3 virus in Jurkat T cells." (PMID 29717016, 2018). "However, SUN2 has also been demonstrated to be an essential host factor for promoting the infection of HIV-1 and HIV-2 in human primary CD4+ T cells and MDDCs." (PMID 29717016, 2018).
infection (continued). "Due to difficulties in infecting resting primary CD4+ T cells in vitro, it will be difficult to establish whether SUN2 has additional cofactor roles in infection." (PMID 29056936, 2017). "A series of central questions therefore arises from this work, including addressing the basis for assay-dependent differences between viral strains and understanding why infection by viruses such as NL4.3 is reduced by either SUN2 overexpression or endogenous gene knockout." (PMID 28747499, 2017). "In agreement with the inability of SUN1 and SUN2 to block infection of HIV-1 viruses bearing the capsid changes G208R or P207S, we saw that SUN1 and SUN2 showed decreased binding to capsid bearing G208R or P207S changes when compared to wild type." (PMID 34580332, 2021). "In contrast, SUN2 does not affect the infection of non-flaviviridae RNA viruses." (PMID 38177122, 2024). "We propose here that the INM components SUN1 and SUN2, two members of the linker of nucleoskeleton and cytoskeleton (LINC) complex, may interact with incoming HIV-1 replication complexes and affect key steps of infection." (PMID 28747499, 2017). "Altogether, our findings show that progression of infection led to downregulation of the key regulator of cytoskeleton–nucleus force transmission, the LINC complex protein SUN2, but did not significantly alter the expression of nuclear lamina proteins." (PMID 41557685, 2026).
myopathies (2 papers, 2014 to 2017). "Screening of the SUN1 and SUN2 genes in a large cohort of patients with EDMD and phenotypically related myopathies identified SUN1 and/or SUN2 variants in several patients." (PMID 25210889, 2014). "We have identified a total of 11 SUN1 and 7 SUN2 rare, non-synonymous variants in our cohort of EDMD and related myopathy patients." (PMID 25210889, 2014). "Using a candidate approach, we have identified putative disease-causing variants in the SUN1 and SUN2 genes, also encoding LINC complex components, in patients with EDMD and related myopathies." (PMID 25210889, 2014). "Whether the functions of SUN1 and SUN2 in the DDR are connected with their roles in myopathies and other laminopathies is currently unresolved." (PMID 28747499, 2017). "We identified 5 rare, non-synonymous SUN1 and/or SUN2 variants in 3 individuals who lacked mutations in other genes but had EDMD or related myopathy phenotypes." (PMID 25210889, 2014).
cardiac disease (1 paper, 2014). "In other cases, the additional presence of a SUN1/SUN2 mutation was associated with more severe cardiac disease." (PMID 25210889, 2014).
SUN2 also shares sentences with these, for which no sentence is quoted: genetic disease (2 papers); heart failure (2); ovarian carcinoma (2); and glucocorticoid deficiency (1); anemia (1); central nervous system embryonal tumors (1); cervical carcinoma (1); Cirrhosis (1); colorectal cancer (1); conduction disorders (1); congenital myasthenia (1); Duchenne muscular dystrophy (1); embryonal tumors (1); ependymoma (1); head and neck squamous cell carcinoma (1); Hepatitis (1); Hutchinson-Gilford progeria syndrome (1); kidney cancer (1); kidney disease (1); leukemia (1); lung adenocarcinoma (1); mandibuloacral dysplasia (1); neurodevelopmental disorder (1); Néstor-Guillermo Progeria Syndrome (1); pancreatic cancer (1); peripheral neuropathy (1); Renal cyst (1); schistosomiasis (1); schizophrenia (1).